CXCR3 (C-X-C motif chemokine receptor 3)
Diseases named in the same sentence as CXCR3 in open-access papers (continued):
Sharing a sentence is not in itself a finding about the gene and the disease.
tumor (continued). "Similarly, the downregulation of CSF2, CXCR3, and TNFSF14 in PBMCs from CRC patients suggests a potential impairment in immune activation and anti-tumor responses." (PMID 40484866, 2025). "Therefore, certain tumor cells with a high expression of CXCL10 and CXCR3 have stronger metastatic and invasive capabilities." (PMID 40145607, 2025). "Cxcr3 expression was relatively specific to CD4+ T cells and increased following anti-PD-L1 treatment, and an increase in CD4+ T cells was evident in the tumour core in anti-PD-L1-treated tumours." (PMID 40523200, 2025). "Expression analysis of key regulators of cell migration (CXCR3, CCR7, CXCR5 and ITGAL, which encodes LFA1, an alias protein name) within these groups revealed significant upregulation of CCR7 in a subset of tumor-infiltrating SH2D2A-positive T cells and CXCR3 in infiltrating SH2D2A-positive T cells." (PMID 41394860, 2025). "CXCR3 may influence HCC progression by promoting tumor cell proliferation and migration, as well as modulating the activity of immune cells within the tumor microenvironment." (PMID 40786052, 2025). "Researchers had identified CXCR3+CD8+T cells and CD11c+ antigen-presenting cells in TME through single-cell sequencing and genomic analysis, and explored the application of circulating tumor DNA (ctDNA) in efficacy monitoring." (PMID 40276056, 2025). "In certain cancers, ‎CXCL10/CXCR3 signaling via the PI3K/Akt pathway helps cancer cells evade immune surveillance, allowing them to evade apoptosis and promote angiogenesis, which in turn promotes tumor ‎survival and spread." (PMID 40760734, 2025). "All these combined effects may contribute to the high absolute tumor uptake of [64Cu]Cu-NOTA-α-CXCR3 and thus mask small, but significant differences of in CXCR3-mediated radiotracer uptake by CXCR3-positive T cells in the TME." (PMID 39196448, 2024). "In addition, IP-10 can engage with the cell surface chemokine receptor 3 (CXCR3) to inhibit the formation of blood vessels and bone marrow colonies to achieve the ultimate anti-tumor effect." (PMID 38680495, 2024). "Th1 cells express CXCR3, and lack of CXCR3 expression on Th2 cells suggests that the enrichment of these cells in the tumor is possibly due to an indirect effect of CXCL9/10 that alters the soluble milieu of the TME." (PMID 38518770, 2024). "In addition to facilitating effector T cell infiltration into the tumor, the CXCL9/CXCL10/CXCR3 signaling cascade is required for optimal T cell activation." (PMID 38518770, 2024). "However, to prove CXCR3-specificity of [64Cu]Cu-NOTA-α-CXCR3 uptake in lymphoid tissues, detailed biodistribution and imaging studies were performed in MC38 tumor bearing mice." (PMID 39196448, 2024). "Additionally, immune cells attracted by chemokines, such as CXCR3 and CCR5/4, can induce apoptosis in tumor cells through the secretion of effector cytokines, such as granzyme B, which exert a cytotoxic effect and elicit an antitumoral response." (PMID 39769501, 2024). "Furthermore, Tregs expressing CXCR3 co-localize with DCs producing CXCL9 in tumors, which affects the presentation of tumor-derived antigens and dampens the activity of anti-tumor CD8+T cells." (PMID 39290699, 2024). "This identified multiple tumour ligands, whose expression was correlated with cellular infiltrates, for further exploration in HGSOC (e.g., expression of CXCL10 correlated with RCTD scores for CXCR3-expressing T cells)." (PMID 38570491, 2024). "Under the chosen experimental conditions, no significant therapy-related change in tumor uptake of [64Cu]Cu-NOTA-α-CXCR3 was observed." (PMID 39196448, 2024). "Our studies indicate that the local production of chemokine IP-10, possibly through its receptor CXCR3 expressed on our patient’s CAR-T, could potentially have mediated the local accumulation of functionally suboptimal anti-tumor T cells." (PMID 38349430, 2024).
tumor (continued). "All of these findings demonstrate that CXCR3 can promote tumor growth and migration and has a negative effect on prognosis." (PMID 39429695, 2024). "Moreover, in our investigation into Gsdmc downregulation, we discovered a notable increase in Cxcl9 expression, crucial for recruiting anti‐tumor immune cells like cytotoxic T cells and NK cells via the CXCL9/CXCR3 axis." (PMID 39297408, 2024). "In the tumor, IFNγ stimulates the production of CXCL9 by tumor and stromal cells, resulting in increased infiltration of CXCR3+ (CXCL9 receptor) cytotoxic immune cells (such as CD8+ T cells and Natural Killer cells) into the tumor that promotes its eradication." (PMID 38698860, 2024). "This is further enhanced by the EPR effect and Fc-glycan-mediated uptake, both of which are well documented for antibody-based tracers, favoring significant non-specific accumulation of the [64Cu]Cu-NOTA-α-CXCR3 macromolecule in the tumor tissue." (PMID 39196448, 2024). "We examined chemokine receptor expression of IgG+plasma cells in obese tumor samples and non-obese tumor samples, including CXCR3, CXCR4 and CXCR5, and found that IgG+plasma cells in obese CRC highly expressed CXCR4." (PMID 38311726, 2024). "Through intratumoral injection, the functional chemokine CXCL10 is continuously expressed in the TME, attracting more CXCR3 + T cells there to kill tumor cells, and the recombinant adenovirus exhibits excellent ability to 'fire up' the TME and improve the anti-tumor efficiency of PD-1 antibodies." (PMID 38243252, 2024). "Adoptive transfer of CXCR3 KO CD8+ T cells did not inhibit tumor growth or infiltration, nor did it respond to anti-PD-1 antibody treatment." (PMID 39543650, 2024). "In our mouse tumor models, functional Cxcl11, the third ligand for CXCR3, is lacking in C57BL/6 mice, hence subsequent efforts will not focus on Cxcl11." (PMID 39316363, 2024). "The expression of CXCR3 and CXCR4 has been shown to be downregulated upon activation and antigen exposure, which supports the notion that DP CD8+ T cells with lower expression of CXCR3 and CXCR4 encounter their cognate tumor antigen." (PMID 38335302, 2024). "Moreover, CXCR3 KO in CD8+ T cells reduce their activation and cytotoxic capacity, thereby accelerating tumor growth compared to the wild type." (PMID 39543650, 2024). "CXCR3, a receptor for the chemokine CXCL11, demonstrates strong anti-tumor activity in vivo." (PMID 39139574, 2024). "Thus inflammatory precursors from PBMC expressing CXCR1, CXCR3 and CX3CR1 selectively enter inflamed tumor tissues." (PMID 38390333, 2024). "Evaluation of TDLNs following IT CXCL9/10-DC therapy in KPL-3M tumor-bearing mice showed enhanced proliferation of both CD4+ and CD8+ T cells, ascertained by Ki67+ staining, and an increased T cell effector polarization, determined by CXCR3 expression." (PMID 38518770, 2024). "Together, these results imply that reduced T-cell infiltration into tumors was responsible for the decreased therapeutic effect of CD3xTRP1 in CXCR3 KO mice, suggesting that homing of T cells towards the tumor is necessary for efficacious CD3 bsAb therapy in this “cold” tumor model." (PMID 38167722, 2024). "We found that the interaction between macrophages and effector CD8+T cells through the CXCL10/CXCR3 pathway in the tumor microenvironment (TME) of the non-ablation zone was required." (PMID 36900218, 2023). "Expression of CXCR3, CXCR6, CCR2, and CCR5 differed between trNK cells, ILCs, CD8+ TRM cells, and CD4+ TRM cells, as well as between locations within the tumor and tumor-distal lung tissue." (PMID 37448786, 2023). "The frequency and number of tetramer + T cells were similar between Cxcr3+/+ and Cxcr3−/− mice, suggesting that increased tumor cell dissemination was not due to a deficit in maintaining tumor-specific T cell quantity." (PMID 36472588, 2023).
tumor (continued). "In addition to inducing effector Th1 cells, CXCL10 can also recruit CXCR3+CD8+T cells to the tumor site and promote these cells to produce Granzyme B, which enhances the anti-tumor effect." (PMID 36900218, 2023). "Additionally, responding patients had a lower tumor burden and displayed the expression of chemokine receptors (CCR7, CCR6, CXCR4, CXCR3, and CXCR5) on CD4+ T cells." (PMID 37174069, 2023). "Combining the two databases, the mRNA levels of CXCR3,4,5 were found to be significantly higher in GBM tissues than in normal tissues, suggesting that these factors may have a relevant role in GBM tumor development." (PMID 37626511, 2023). "In addition, CXCL9, a ligand of CXCR3 that promotes adhesion to vascular endothelium for CXCR3, promotes the release of IFN-ɤ from CD8-positive T cells in the tumor by anti-VEGF antibody and anti-PD-1 antibody." (PMID 37046727, 2023). "The amplification of CXCR3+ stem-like cells was coupled with a substantial increase in effector-like but not terminally exhausted cells in tumor tissue." (PMID 37045833, 2023). "Whereas, it also reminds us when combined NK cell-based ACT and radiotherapy in solid tumor treatment, we should detect CXCR3 and its ligands expression in cancer cells, and pathways (as Ras/ERK or PI3K/AKT) inhibitors should be introduced to prevent tumor metastasis in time." (PMID 38264648, 2023). "Strong increases toward the tumor center were observed for CXCR3+CXCR6+ cells (population 13) and CCR5+CXCR3+CXCR6+ CD8+ TRM cells (population 9), concurrent with a decrease in CCR5 single-positive (population 12) as well as CCR2+CCR5+CXCR6+ (population 3) CD8+ TRM cells." (PMID 37448786, 2023). "CXCL10/CXCR3 mainly activates downstream signaling pathways (including MAPK and PI3K/Akt) and then produces biological effects, such as promoting angiogenesis and inhibiting tumor-related immunity." (PMID 36782176, 2023). "Whereas N803 in combination with vaccine promoted circulating activated CD8+ T cells with augmented expression of the trafficking chemokine receptor CXCR3, CD8+ T cells showed poor tumor infiltration and granzyme B expression in the TME, resulting in modest antitumor efficacy." (PMID 37371081, 2023). "As expected, CXCR3 and KLRG1 were decreased in tumor vs. spleen." (PMID 36472588, 2023). "In PDA, tumor-specific T cell frequency and number were not significantly different among Cxcr3+/+ vs. Cxcr3−/− mice at both timepoints." (PMID 36472588, 2023). "Related work has shown CXCR3 and its ligands to be among a host of genes whose expression is upregulated in HPVOPC via the increased activity of PI3K gamma, which functions as a molecular switch that promotes immunosuppression during tumor growth." (PMID 37686653, 2023). "In non-tumor-bearing mice, Cxcr3 was expressed by memory and effector T cells but not naïve T cells, as expected." (PMID 36472588, 2023). "The elevated levels of Ifng further induce antitumor immune activity in tumors, leading to increased CXCL9 expression from tumor cells; CXCL9 then recruits CXCR3+ immune cells, such as cytotoxic CD8+ T cells and NK cells, into cancers to increase effector immune cell infiltration." (PMID 37253006, 2023). "Given the upregulation of CXCR3 on ex vivo expanded NK cells and their ability to migrate towards tumors expressing exogenous CXCL10, STING agonists could enhance their tumor homing." (PMID 38022679, 2023). "Thus, Cxcr3 is dispensable for CD8 T cell infiltration into orthotopic PDA and had negligible impact on overall tumor control." (PMID 36472588, 2023). "Subsequently, within the tumour and upon antigen stimulation, these CXCR3+ TEM preferentially differentiate towards PD-1 negative CD8 TEMRA, the proposed effectors of direct anti-tumour cytotoxicity within the TME." (PMID 38030622, 2023). "We tested the hypothesis that the CXCR3 chemokine axis has a pro-tumor effect in HPVOPC and is a targetable driver of tumor growth in an athymic mouse model." (PMID 37686653, 2023).
tumor (continued). "Meanwhile, since our previous study also showed that IRF1 recruited NK cells and CD8+T cells through CXCL10/CXCR3 axis, we investigated whether IRF1-MICA signaling recruited anti-tumor immune cells via the CXCR3 receptor." (PMID 36765808, 2023). "Chemokine CXCL10, as an interferon-inducible protein, is most likely involved in the thermal-ablation-induced expression of CXCL10 by TAM1, which stimulates interferon secretion and recruits CXCR3+CD8+T cells to infiltrate into tumor tissues, thus exerting anti-tumor effects." (PMID 36900218, 2023). "Recently, macrophage-expressing C-X-C motif chemokine receptor 3 (CXCR3) ligands including CXCL9 were found to recruit CD8-positive T cells and be indispensable for anti-tumour efficacy of ICIs, suggesting the importance of cytocidal macrophages working against both tumour cells and beta cells." (PMID 35511238, 2022). "The low intracellular content of ROS is related to the enhanced expression of the homing receptors CCR2, CXCR3 and CCR7, which promote both entry and accumulation of CLL cells in the pro-survival tumor microenvironment of lymphoid organs, eventually enhancing leukemic cell survival." (PMID 35847884, 2022). "The fraction of tumor-infiltrating immune subpopulations was determined using CIBERSORT, and 21 different types of immune cells in tumor tissues were created to further support the link between CXCR3 expression and the TME." (PMID 35847936, 2022). "The same group later reported that single-agent administration of another novel STING agonist (ADU-S100) decreased tumor burden and activated the murine immune system by increasing CTL tumor infiltration and decreasing TAMs and Tregs in a CXCR3-dependent fashion." (PMID 36077755, 2022). "The absence of CXCR3 seems not to interfere with the ex vivo-specific lysis against tumor cells (OT-I CD8 T cells/OVA-expressing tumor cells) nor with the IFNγ, TNFα or Granzyme B expression." (PMID 36429101, 2022). "They propose that Dipeptidyl peptidase (DPP4) inhibition increases tumor content of CXCL9/10, which recruits CXCR3 + NK and T cells, and DPP8/9 inhibition activates the inflammasome, resulting in proinflammatory cytokine release and Th1 response, further enhancing the CXCL9/10-­CXCR3 axis." (PMID 36479091, 2022). "Tumor metastasis to the lung is facilitated by total NK cell depletion, but not by anti-CXCR3 antibodies, implying a role for other chemokine receptors." (PMID 35844626, 2022). "This upregulation of CXCR3 on CD8+ T cells enhanced their migration toward the IFNγ-inducible ligands CXCL9, -10, and -11 to stimulate trafficking into the tumor, and presumably also increased trafficking of CD4+ T and NK cells, which are also regulated by this mechanism." (PMID 36382146, 2022). "For instance, CXCR3+ lymphocytes are attracted by CXCL9, which is secreted by stromal cells in gastric and ovarian cancer, thus facilitating the entrance of lymphocytes into the tumor sites." (PMID 36275816, 2022). "Our standard process for dissociation of tumour tissue specimens using gentleMACS reagents was found to significantly diminish CXCR3 and CCR6 staining (data not shown)." (PMID 35464424, 2022). "His team use Glycoprotein - A repetitions predominant antibody treatment to reduce the typical TGF signaling pathway in tumor-infiltrating immune cells, prevent T cell exhaustion, and promote CD8+ T cell migration to TME in a CXCR3-dependent manner to enhance anti-tumor effects." (PMID 36479091, 2022). "This analysis showed, in tumor samples, an increased percentage of CCR6+ CD8+ T cells expressing both CCR5 and CXCR3 (p < 0.01) and a decrease of Th17 and Tc17 cells expressing only CCR5 (p < 0.01 and p < 0.0001, respectively) and an increase of Tc17 cells expressing only CXCR3 (p < 0.0001)." (PMID 36551555, 2022).
tumor (continued). "To further evaluate whether the reduced tumor growth and increased T cell density observed in GPR182−/− mice were dependent on the CXCR3 pathway, we treated mice with a CXCR3 blocking mAb throughout YUMM1.7 tumor inoculation." (PMID 35013216, 2022). "Moreover, tumor-infiltrating DCs, especially CD103+ DCs, boost the infiltration of effector T cells into the tumor by producing CXCL9/10 and hence recruiting CXCR3+ T cells." (PMID 33603130, 2022). "CXCL10 is highly expressed in mouse models of plasmacytoma and mammary adenoma, while it has low expression in mouse models without thymus; therefore, the anti-tumor effect of the CXCL10/CXCR3 pathway is thought to be T lymphocyte-dependent." (PMID 36479091, 2022). "Thus, the ex vivo selection or enrichment of CXCR3+ CD8+ T cells appears as a promising strategy for optimizing the efficacy of therapeutic concepts, which are based on the adoptive transfer of tumor-targeting T cells in the clinical context of CRC." (PMID 36428508, 2022). "(ii) Antitumor immune-related molecules including CXCL10, CXCL9, CXCR3, CCL5, and CCL4 belong to the chemokine family and have been reported in several studies to recruit immune cells such as cytotoxic T lymphocytes (CTL) and NK cells to kill tumor cells." (PMID 35479936, 2022). "In this evaluation, we could also verify that the tumor size is significantly correlated with the presence of Th17/Th1 (CD4+ CCR6+ CCR5+ CXCR3−) and Th17 cells (CD4+ CCR6+ CCR5− CXCR3−) cells in the TME." (PMID 36551555, 2022). "Indeed, in many organs, including breast, ovary, prostate, lung, kidney, as well as within the gastrointestinal tract, tumor progression is likewise affected by CXCR4, CXCR3, and CXCR7." (PMID 36539774, 2022). "In anti-PD-1-treated mice, CXCR3 and its ligands are essential in generating CD8+ T lymphocyte responses, and the production of CXCL9 promotes anti-PD-1-induced anti-tumor responses, suggesting that CXCR3 facilitates the interaction between DCs and T lymphocytes in the TME." (PMID 36479091, 2022). "This pro-tumoral effect of CXCR3+ Tregs was also observed in HCC, where a correlation could be made between the infiltration of CXCR3+ Tregs in the TME induced by CXCL10 and increased tumor growth and HCC recurrence after liver transplantation." (PMID 33924428, 2021). "Because CXCR3 expression was primarily in responder T and NK cells and absent from tumor cells, it appears to have an antitumor effect in this context and thus would induce T and NK cell activation." (PMID 34433873, 2021). "CXCR3 exerts its biological effects through engagement by three IFN-γ inducible ligands (CXCL9, CXCL10 and CXCL11) that are mainly secreted by monocytes, endothelial cells, fibroblasts and tumor cells." (PMID 33924428, 2021). "Immunologic participation in complexes with trafficking chemokine receptors CCR2 and CXCR3 became significant in tumor but not plaque MF, which coincided with the observed influx of TILs observed with multispectral imaging." (PMID 34885092, 2021). "The CXCR3 inhibitor did not alter primary tumour growth when tumour volumes were compared to vehicle-treated animals." (PMID 33795809, 2021). "Intriguingly, only knockout of TLR4, instead of CXCR3, could obviously decrease the MDSC mobilization at the early stage and reduce tumor progression at the late phase." (PMID 33990548, 2021). "Circulating CXCL9 is a predictor of poor prognosis in HNSCC;51 however, in the context of CXCR3 expression in bintrafusp alfa responder tumors, it has the potential to induce antitumor immunity rather than promote tumor expansion." (PMID 34433873, 2021). "Thus, immunofluorescence staining of the chemokine receptors CXCR3 and CCR4 confirms the low Th1:Th2 ratio and thereby the Th2-skewing of the immune landscape in tumor stroma and TLS." (PMID 34868011, 2021).